TNF (tumor necrosis factor)
Diseases named in the same sentence as TNF in open-access papers (continued):
Sharing a sentence is not in itself a finding about the gene and the disease.
Insulin resistance (continued). "Our previous clinical study showed the effectiveness of Eriomin® in reducing fasting glucose, glucose intolerance, insulin resistance (HOMA‐IR), glycated hemoglobin (HbA1c), glucagon, C‐peptide, HSCRP, IL‐6, and TNF‐α." (PMID 37970408, 2023). "In TNFα−/− mice, the development of early signs of MASH and insulin resistance was significantly attenuated compared to wild-type animals." (PMID 37683301, 2023). "In ob/ob mice, the injection of anti-TNFα antibodies improved steatosis and inflammation as well as activity of c-Jun N-terminal kinase (JNK), shown to be critical in promoting insulin resistance, was dampened." (PMID 37683301, 2023). "However, the role of TNF in the initiation of insulin resistance remains unclear." (PMID 36766750, 2023). "Our results were consistent with other studies that reported that TNF-α, FFAs, and ROS activated JNK and promoted initiation and progression of insulin resistance and the development of NAFLD." (PMID 36677937, 2023). "Therefore, increases in plasma LPS and pro-inflammatory cytokines such as interleukin-6 (IL-6) or tumor necrosis factor-α (TNF-α) levels could lead not only to insulin resistance but also to decreased Sg, both of which may result in postprandial hyperglycemia and subsequent reactive hypoglycemia." (PMID 37367911, 2023). "During the weight gain process, the hypertrophic adipocytes increase the production of Tumor necrosis factor alpha (TNF-α), which assumes the character of a pro-inflammatory molecule and induces systemic insulin resistance." (PMID 37296485, 2023). "Tumor necrosis factor-α and interleukin (IL)-6 are derivatives of acute-phase proteins, including CRP, and both potentially contribute to insulin resistance by affecting intracellular insulin signaling." (PMID 37448125, 2023). "Placental hormones such as placental growth hormone, human placental lactogen, leptin, and tumor necrosis factor-α (TNF-α), which are responsible for insulin resistance, are thought to play a role in fat accumulation during pregnancy." (PMID 37569340, 2023). "Insulin resistance (HOMA-IR, QUICKI), HOMA-β and elevations in plasma inflammatory cytokine levels (TNF-α, IL-6 and HMGB-1) were all attenuated by galantamine." (PMID 37731032, 2023). "TNF-α induces phosphorylation of IRS-1 on serine in place of tyrosine residues and promotes insulin resistance." (PMID 36860845, 2023). "Two kinases displayed impaired insulin-activation in three or more insulin resistance models, ERK (CI, TNF, AA), and CDK5 (CI, TNF, MPQ, AA)." (PMID 36808134, 2023). "Markers of inflammation, such as serum C-reactive protein (CRP), interleukin (IL)-6 and tumor necrosis factor (TNF)-α, are, in fact, significantly elevated in patients with insulin resistance." (PMID 36675217, 2023). "LPSs can induce inflammation in fat cells by increasing TNF-α and MCP-1 levels, thereby inducing insulin resistance." (PMID 38066566, 2023). "•A genetic deletion of TNFα attenuates the development of early signs of MASH and insulin resistance." (PMID 37683301, 2023). "A recent study indicated that concentrations of tumor necrosis factor alpha (TNF-α) and interleukin 6 (IL-6) are higher in females with PCOS, especially among those cases that present with signs of insulin resistance." (PMID 37569074, 2023). "Accumulated visceral adipose tissue produces more inflammatory cytokines, such as tumor necrosis factor alpha (TNF-a), interleukin-6 (IL-6) and IL-1b, and less adiponectin, which induces systemic insulin resistance." (PMID 37895151, 2023). "Probiotics have positive effects on inflammatory liver damage mediated by c-Jun N-terminal kinase (JNK) and Nuclear Factor kappa B (NF-κB), which was correlated with Tumor Necrosis Factor-alpha (TNF-α) regulation and insulin resistance." (PMID 37834367, 2023). "This TNF-α induction leads to the PP2C-mediated inactivation of AMPK, which increases the fatty acid levels and, potentially, insulin resistance." (PMID 36902014, 2023).
Insulin resistance (continued). "On the other hand, inflammatory cytokines, such as interleukin-6 (IL-6) and tumor necrosis factor-alpha (TNF-α), can affect insulin sensitivity, glucose, and lipid metabolism, potentially leading to insulin resistance." (PMID 37841266, 2023). "In such a context, systemic and local inflammation with elevated levels of cytokines, TNF-α, and interleukins, IFN γ, insulin resistance and oxidative stress play a role in exacerbating the vascular remodeling process involved in pulmonary hypertension." (PMID 36993998, 2023). "Socs3 can be induced by certain inflammatory cytokines (e.g., TNFα and IL6) to contribute to inflammation-mediated insulin resistance in the liver and adipose tissue." (PMID 36709676, 2023). "Adipose tissue secretes proinflammatory cytokines, such as interleukin-6 (IL-6) and tumor necrosis factor-alpha (TNF-α), which contribute to insulin resistance and systemic inflammation." (PMID 37868505, 2023). "The activation of the TNF and IL1B signaling pathways promotes insulin resistance and fat deposition in hepatocytes." (PMID 37602516, 2023). "In this study, HFD-enhanced TNF-α, ox-LDL, IL-6, and MMP-9 levels, whereas SG markedly downregulated proinflammatory cytokines and reversed insulin resistance, resulting in vascular protection." (PMID 36982743, 2023). "The reduction in adipose tissue decreases the release of proinflammatory adipokines, such as tumor necrosis factor-alpha (TNF-α) and interleukin-6 (IL-6), which contribute to a low-grade systemic inflammation and insulin resistance." (PMID 38201924, 2023). "A recent report suggested that TNF-α plays a casual role in the onset of fructose-induced NAFLD/NASH and insulin resistance in mice." (PMID 37095192, 2023). "Neuroinflammation is due to the release of inflammatory cytokines, such as tumor necrosis factor (TNF)-α, interleukin (IL)-6, IL-12, and IL-1β, which is promoted by oxidative stress, insulin resistance, and Aβ-induced activation of microglial cells." (PMID 37511061, 2023). "The main effector molecule in the TNF pathway is TNF-α, which binds to tumor necrosis factor receptor (TNFR) to produce JNK and NF-κB, thereby inducing inflammatory response and insulin resistance." (PMID 36866869, 2023). "Interleukin-6 (IL-6) and tumor necrosis factor-alpha (TNF-α), inflammatory molecules released during immune responses, can induce insulin resistance in peripheral tissues, particularly adipose tissue and the liver." (PMID 38140151, 2023). "Adipose tissue produces a large number of pro-inflammatory cytokines, such as TNF-α, monocyte chemotactic protein-1 (MCP-1), IL-6, and C-reactive protein, which promote chronic inflammation, decreased muscle protein synthesis, and insulin resistance." (PMID 37424859, 2023). "Body mass index (BMI), homeostatic model assessment of insulin resistance (HOMA-IR), tumor necrosis factor-α (TNF-α), malondialdehyde (MDA), total superoxide dismutase (t-SOD) activity, and plasminogen activator inhibitor-1 (PAI-1) were measured." (PMID 37503477, 2023). "The ratio of M1-like to M2-like macrophages is increased substantially resulting in copious secretion of proinflammatory mediators such as TNFα, IL-6, IL-1β, MCP-1, fetuin-A (FetA), etc. further worsening insulin resistance." (PMID 36718668, 2023). "Increased placental expression of TNFα and IL-6 in GDM worsens local inflammation and insulin resistance." (PMID 38288471, 2023). "There were also links to two established mediators of insulin resistance: TXNIP and tumor necrosis factor-α (TNFα)." (PMID 38292764, 2023). "At the same time, inflammatory cytokines such as tumor necrosis factor alpha (TNF-α) are increased in various tissues in diabetes, which contributes to insulin resistance and reflects the severity of the disease." (PMID 37974282, 2023).
Insulin resistance (continued). "Moreover, TNF-α may potentiate hepatic insulin resistance, thus interconnecting inflammatory with metabolic signals and possibly contributing to the development of NAFLD-related comorbidities, including cardiovascular disease, hepatocellular carcinoma, and extra-hepatic malignancies." (PMID 37407724, 2023). "Insulin resistance plays an vital role in NAFLD pathogenesis, and various inflammatory factors such as IL-6 and TNF-α can promote insulin resistance, leading to NAFLD occurrence and development." (PMID 36778868, 2023). "Inflammatory cytokines, such as interleukin-6 (IL-6) and tumor necrosis factor-alpha (TNF-α), are increased in individuals with metabolic syndrome, and they contribute to the development of insulin resistance and other metabolic abnormalities." (PMID 37445955, 2023). "Several bona fide GSK3 substrates displayed impaired dephosphorylation across insulin resistance models, such as S641 on glycogen synthase (CI and AA), and S86 and S90 on the histone acetyltransferase Kat5 (CI, DEX, TNF, and AA)." (PMID 36808134, 2023). "Inflammatory cytokines, such as tumor necrosis factor-alpha (TNF-α) and interleukin-6 (IL-6), can potentially hinder insulin signaling in renal cells, resulting in insulin resistance." (PMID 37868469, 2023). "Hesperidin treatment also improved insulin resistance (Homeostasis model of insulin resistance (HOMA-IR) values) and reduced pro-inflammatory markers TNF-α and IL-6 levels." (PMID 38234970, 2023). "Recruited inflammatory cells, especially M1 macrophages, release proinflammatory cytokines, such as tumor necrosis factor alpha (TNF-α) and IL-1β, resulting in insulin resistance." (PMID 36370846, 2022). "Systemic markers such as CRP, TNF-α, and IL-6 play an important role in both the progression of COPD and the development of insulin resistance." (PMID 35628022, 2022). "HDL-C, LDL-C, TC, TG, CRP, TNF-α, and IL-6 levels were abnormal in the HFD group, indicating harm to lipid metabolism and inflammation after a HFD-induced insulin resistance diet." (PMID 35907080, 2022). "First, insulin resistance is common in CKD, possibly related to pro-inflammatory cytokines such as interleukin-6 and tumor necrosis factor-⍺ and oxidative stress that are involved in intracellular mechanisms of insulin resistance." (PMID 35189851, 2022). "From the hypothesized contribution of HK2-linked unscheduled glycolysis to the development of insulin resistance, the activation of the UPR provides a key contributory role, increasing the expression of established mediators of insulin resistance, TXNIP and tumor necrosis factor-α (TNFα)." (PMID 35216280, 2022). "They secrete pro-inflammatory cytokines (TNF-α, IL-6, IL-1β, IL-12, and MCP-1), which not only have a role in promoting insulin resistance but also recruit other immune cells to the site of inflammation." (PMID 36248900, 2022). "This is because BRD2 knockdown attenuates TNF-α-mediated inflammatory mRNA expression in adipocytes, indicating that BRD2 is required for TNF-α signaling and the initiation of insulin resistance in vitro." (PMID 36015180, 2022). "In a similar study, insulin resistance in streptozotocin (STZ)-induced type 2 diabetic rats was significantly improved by inhibiting hepatic NF-κB activation and tumor necrosis factor-α (TNF-α) level after two month of aspirin administration (120 mg/kg/day)." (PMID 35213966, 2022). "On the other hand, tumor necrosis factor-alpha (TNF-α) induces adipocyte apoptosis and promotes insulin resistance by the inhibition of insulin receptor substrate 1 signaling pathway." (PMID 35669072, 2022). "The TNF-α/JNK pathway is also activated in T2D, leading to peripheral insulin resistance and contributing to pancreatic β-cell apoptosis and increased oxidative stress." (PMID 36499613, 2022). "Previously, the overproduction of IL-6 and TNF-α in T2DM patients led to the development of vascular inflammation and insulin resistance." (PMID 36276816, 2022).
Insulin resistance (continued). "The body weight, insulin resistance index, and the levels of FBG, C-Peptide, IL-6, TNF-α, and MDA in the serum of HFD mice significantly decreased (P < 0.05)." (PMID 35571892, 2022). "Higher TNFα levels have also been reported in the same subjects, consistent with evidence that a high AGE level increases inflammation and insulin resistance." (PMID 36558414, 2022). "TNFα released into the tissue is recognized by its receptors TNF-R1 to stimulate lipolysis and apoptotic processes and TNF-R2, involved in insulin resistance through inhibition of insulin signaling." (PMID 35276970, 2022). "Mast cells, which secrete paracrine and autocrine proinflammatory cytokines such as tumor necrosis factor (TNF), IL-33, and IL-6, participate in the mechanism of insulin resistance by activating kinases." (PMID 35887276, 2022). "The presence of a periodontal infection elevates the plasma levels of TNF-α, IL-6 and C-reactive protein (CRP) and insulin resistance markers such as HOMA-IR in periodontitis patients." (PMID 35327570, 2022). "Second, silver carp and salmon phospholipids contain n-3 PUFA, which can significantly reduce the serum IL-6, TNF-α, and MCP-1 levels of high-fat mice, inhibiting the body’s inflammatory response and thus improving insulin resistance and metabolic syndrome." (PMID 36291067, 2022). "Higher levels of IL-6, TNF-α, and C reactive protein (CRP) have been found in diabetic patients, and it is known that high CRP levels are correlated to insulin resistance due to impaired intracellular insulin signaling." (PMID 35996409, 2022). "The histological and biochemical improvement were associated with lower levels of two nuclear factors regulated by tumor necrosis factor (TNF): Jun N-terminal kinase (JNK) and nuclear factor B (NF-B), both involved in the development of insulin resistance." (PMID 36139402, 2022). "Numerous inflammatory cytokines and mediators, including tumor necrosis factor-α (TNF-α), interleukin-6 (IL-6) and monocyte chemoattractant protein 1 (MCP-1), are upregulated during insulin resistance." (PMID 35327570, 2022). "Proinflammatory cytokines including tumor necrosis factor-alpha (TNF-α) and IL-6 have been shown to affect insulin signaling, which can lead to insulin resistance." (PMID 35732620, 2022). "AX enhanced satiety after a meal and decreased homeostatic model assessment of insulin resistance (HOMA-IR), while MCC reduced tumor necrosis factor-α and fecal calprotectin." (PMID 35562794, 2022). "Regular physical activity suppresses TNF-α and thereby protects against TNF-α-induced insulin resistance." (PMID 35625533, 2022). "Hypertrophic adipocytes produce abnormal adipokines and cytokines, such as TNF-alpha, MCP-1, FFA, IL-6, and resistin, which inhibit insulin signaling in hepatocytes and induce insulin resistance." (PMID 36615686, 2022). "These macrophages predominantly present the M1 pro-inflammatory phenotype and promote inflammation by releasing granulocyte-macrophage colony-stimulating factor (GM-CSF), tumor necrosis factor alpha (TNF-α), IL-1β or IL-6, contributing to insulin resistance." (PMID 35807797, 2022). "IL-6 and TNF-α have an inhibitory effect on glucose transporter type-4 (GLUT-4) expression, and their increase leads to insulin resistance." (PMID 36355818, 2022). "In this study we found significant reductions in the exercise group compared with usual care in pro-inflammatory biomarkers including TNF-α, IL-6, IL-8, hs-CRP or leptin, and those related to insulin resistance." (PMID 35795051, 2022). "IL-6 can promote the production of TNF-α in the inflammatory response, whereas TNF-α from adipose tissue and placenta can promote insulin resistance in pregnant women, which is closely related to the pathogenesis of GDM." (PMID 35415242, 2022). "In conclusion, all types of AA extracts (i.e. hot and cold-water and alcoholic), improved insulin resistance through reduction of LDL/HDL ratio, free fatty acids, TNF-alpha, and IL-6." (PMID 35145895, 2022).
Insulin resistance (continued). "Our main findings unveiled that FMT prevented body weight gain, reduced albuminuria and tumor necrosis factor-α (TNF-α) levels within the ileum and ascending colon, and potentially ameliorated insulin resistance in BTBRob/ob mice." (PMID 35409202, 2022). "M1 ATMs form the “crown like” structure around dead adipocytes and produce TNF-α, IL-6, and CCL2, accelerating chronic inflammation and insulin resistance." (PMID 35885044, 2022). "Interestingly, TNF-α can induce insulin resistance in mice, and a recent study in flies observed that fat body-secreted Egr targets insulin-producing cells to inhibit the expression of dILPs, indicating a conserved role for TNF-α/Egr signaling in antagonizing insulin/IGF signaling." (PMID 35319749, 2022). "Therefore, the impact of plasma TNFα measured in the study on insulin resistance is unknown." (PMID 36364884, 2022). "It increased the factors involved in insulin resistance, including blood levels of FFA, LDL/HDL ratio, TNF-alpha, IL-6, and HOMA-IR; however, these changes were reversed by metformin and water and alcoholic extracts of AA." (PMID 35145895, 2022). "The M1 macrophages produce pro-inflammatory cytokines, such as Tumor Necrosis Factor (TNF)-α, interleukin IL-6 and MCP-1, which contribute to the development of insulin resistance." (PMID 36501129, 2022). "A combination of counter regulatory hormones (e.g., glucagon and growth hormone) and proinflammatory cytokines such as tumor necrosis factor alpha (TNF-α), interleukin-1 (IL-1), and interleukin-6 (IL6) lead to insulin resistance and hyperglycemia." (PMID 35178208, 2022). "The hypertrophic adipocytes and adipose tissues induce pre-inflammatory cytokines, such as tumor necrosis factor α (TNF-α), that prevent insulin signaling and lead to insulin resistance." (PMID 36387872, 2022). "The yellow cluster mainly consists of smooth muscle cells, endothelial cells, oxidative stress, endothelial dysfunction, gene expression, insulin resistance, T-cell, NO, MCP-1, TNF-α, NF-κB, TLRs, TNF, TNF-α, and INF-γ." (PMID 36311729, 2022). "Tumor necrosis factor-α induced phosphorylation of insulin receptor substrate 1 (IRS-1), preventing insulin from binding to the receptor, which consequently led to insulin resistance." (PMID 35433780, 2022). "TLR4 signaling leads to the activation of the NFκB pathway, which results in the secretion of inflammatory mediators (e.g., TNFα, MCP-1, and IL-6) and stimulates insulin resistance." (PMID 35889783, 2022). "The correction of insulin resistance by tRES-HESP in overweight and obese subjects in the HATFF study correlated with improvements in the expression of TXNIP and TNFα." (PMID 35216280, 2022). "Studies have reported that TNF-α is elevated in the adipose tissue of patients with diabetes, and blocking TNF-α can alleviate insulin resistance in vivo." (PMID 35712257, 2022). "Inflammatory responses in the adipose tissues eventually result in elevated levels of several pro-inflammatory cytokines, TNF, IL-6, IL-1, and CCL2, which are responsible for insulin resistance." (PMID 36552725, 2022). "A significant decrease in fasting glycemia (−5%), insulin resistance (−11%), ALP (−8%), glucagon (−13%), IL-6 (−14%), and TNF-α (−20%) was detected." (PMID 35796695, 2022). "Adipose tissue inflammation, along with the increase of pro-inflammatory cytokines such as interleukin 6 (IL‐6) and tumor necrosis factor alpha (TNF‐α), also lead to insulin resistance." (PMID 35546181, 2022). "In the present study, the combination of W. coagulans and EA in food significantly reduced the plasma levels of endotoxins LPS, hs-CRP, Zonulin, TNF-α, and IL-6 and relieved HFD-induced insulin resistance." (PMID 36235858, 2022). "Vescalagin isolated from S. samarangense ameliorated insulin resistance in high-fructose diet-induced hyperglycemic rats and reduced the pancreatic levels of NF-κB, ICAM-1, and TNF-α proteins." (PMID 35684249, 2022).